YWHAE (tyrosine 3-monooxygenase/tryptophan 5-monooxygenase activation protein epsilon)
Description:
Adapter protein implicated in the regulation of a large spectrum of both general and specialized signaling pathways. Binds to a large number of partners, usually by recognition of a phosphoserine or phosphothreonine motif. Binding generally results in the modulation of the activity of the binding partner (By similarity). Positively regulates phosphorylated protein HSF1 nuclear export to the cytoplasm. Plays a positive role in the antiviral signaling pathway upstream of TBK1 via interaction with RIGI. Mechanistically, directs RIGI redistribution from the cytosol to mitochondrial associated membranes where it mediates MAVS-dependent innate immune signaling during viral infection. Plays a role in proliferation inhibition and cell cycle arrest by exporting HNRNPC from the nucleus to the cytoplasm to be degraded by ubiquitination.
Synonyms: 14-3-3E; FLJ45465; HEL2; KCIP-1; MDCR; MDS
Tractability: Small molecule: a structure with a bound ligand is known. Antibody: its Gene Ontology location is reachable by antibodies, with high confidence. PROTAC: UniProt records ubiquitination sites on it; ubiquitination databases record sites on it; its protein half-life has been measured.
Gene: Protein-coding gene on chromosome 17 (1,344,275 to 1,400,255, reverse strand). Ensembl gene ENSG00000108953.
Subcellular location: Nucleus; Cytoplasm; Melanosome
Subcellular location (Human Protein Atlas): Cytosol
Pathways (Reactome):
Cell Cycle: AURKA Activation by TPX2; Chk1/Chk2(Cds1) mediated inactivation of Cyclin B:Cdk1 complex; Loss of Nlp from mitotic centrosomes; Loss of proteins required for interphase microtubule organization from the centrosome; Recruitment of NuMA to mitotic centrosomes; Recruitment of mitotic centrosome proteins and complexes; Regulation of PLK1 Activity at G2/M Transition
Disease: Deregulated CDK5 triggers multiple neurodegenerative pathways in Alzheimer's disease models; SARS-CoV-1 targets host intracellular signalling and regulatory pathways; SARS-CoV-2 targets host intracellular signalling and regulatory pathways
Signal Transduction: NADE modulates death signalling; RHO GTPases activate PKNs; Signaling by Hippo
Cellular responses to stimuli: HSF1 activation; Regulation of HSF1-mediated heat shock response
Vesicle-mediated transport: RAB GEFs exchange GTP for GDP on RABs; Translocation of SLC2A4 (GLUT4) to the plasma membrane
Developmental Biology: Transcriptional and post-translational regulation of MITF-M expression and activity
Organelle biogenesis and maintenance: Anchoring of the basal body to the plasma membrane
Programmed Cell Death: Activation of BAD and translocation to mitochondria
Gene Ontology:
Molecular function: cadherin binding; calcium channel inhibitor activity; calcium channel regulator activity; enzyme binding; histone deacetylase binding; identical protein binding; MHC class II protein complex binding; phosphoprotein binding; phosphoserine residue binding; potassium channel regulator activity; protein binding; protein heterodimerization activity; protein sequestering activity; RNA binding; scaffold protein binding; signaling adaptor activity; transmembrane transporter binding; ubiquitin protein ligase binding; molecular function inhibitor activity; protein domain specific binding; protein phosphatase binding; protein phosphatase inhibitor activity
Biological process: cellular response to heat; cytoplasmic pattern recognition receptor signaling pathway; intracellular potassium ion homeostasis; MAPK cascade; negative regulation of calcium ion export across plasma membrane; negative regulation of protein import into nucleus; negative regulation of toll-like receptor signaling pathway; positive regulation of hippo signaling; positive regulation of protein export from nucleus; protein localization to endoplasmic reticulum; protein localization to nucleus; regulation of cytosolic calcium ion concentration; regulation of membrane repolarization; regulation of potassium ion transmembrane transport; substantia nigra development; intracellular protein localization; intracellular signal transduction; membrane repolarization during cardiac muscle cell action potential; regulation of heart rate by cardiac conduction; regulation of heart rate by hormone; regulation of mitotic cell cycle
Cellular component: cytoplasm; cytosol; endoplasmic reticulum; extracellular exosome; focal adhesion; melanosome; membrane; nucleus; plasma membrane; mitochondrial membrane
Genetic constraint (gnomAD): Loss-of-function variants: 1 observed, 27.09 expected, observed/expected ratio (o/e) 0.0369, 90% interval 0.012 to 0.17. The upper end of that interval is the gene's LOEUF score, 0.17, which puts it in group 1 of 6, group 1 being the genes least tolerant of losing a copy. Missense variants: 119 observed, 316.83 expected, observed/expected ratio (o/e) 0.38, 90% interval 0.32 to 0.44. Synonymous variants: 117 observed, 110.53 expected, observed/expected ratio (o/e) 1.06, 90% interval 0.91 to 1.23.
Homologues: Orthologues: chimpanzee YWHAE (100% identical), dog YWHAE (100% identical), macaque YWHAE (100% identical), mouse Ywhae (100% identical), pig YWHAE (100% identical), tropical clawed frog ywhae (96% identical), zebrafish ywhae1 (96% identical), rabbit YWHAE (95% identical), rat Ywhae (85% identical), Drosophila melanogaster 14-3-3epsilon (85% identical), Caenorhabditis elegans M117.3 (21% identical). Paralogues in human: YWHAZ (68% identical), YWHAB (65% identical), YWHAQ (64% identical), YWHAH (62% identical), YWHAG (61% identical), SFN (59% identical).
Diseases named in the same sentence as YWHAE in open-access papers:
YWHAE is named in the same sentence as 105 diseases in open-access papers, as found by Europe PMC text mining. Sharing a sentence is not in itself a finding about the gene and the disease. The quoted sentences say what the papers report.
breast carcinoma (17 papers, 2013 to 2025). "The gene YWHAE was found associated with tumour size, lymph node metastasis, and poor patient survival in patients with breast cancer." (PMID 35057823, 2022). "We also identified a cluster associated with the extrinsic apoptotic pathway involving PPP2R1A, PPP2R1B and YWHAE, proteins dysregulated in breast cancer." (PMID 39353922, 2024). "YWHAE promoted proliferation and metastasis of breast cancer cells, and regulated proliferation and cell cycle protein D1 through RAF/MAPK and Hippo pathways." (PMID 37821869, 2023). "YWHAE was upregulated in breast cancer cells and patients with overexpressed YWHAE showed a poor survival." (PMID 36467089, 2022). "Overexpression of YWHAE increases the proliferation, migration and invasion ability of breast cancer cells." (PMID 35430805, 2022). "YWHAE was upregulated in breast cancer, high-grade endometrial stromal sarcoma, gastric cancer, and colorectal cancer and associated with poor outcomes." (PMID 34249899, 2021). "In breast cancer, YWHAE expression is related to tumour size, lymph node metastasis, and patient prognosis, as well as breast cancer resistance to chemotherapy." (PMID 34107979, 2021). "Indeed, YWHAE overexpression significantly increases breast cancer cell proliferation, migration, and invasion, whereas reduced YWHAE expression prevents Snail and Twist expression in breast cancer cells." (PMID 34107979, 2021). "To find co-function or regulatory relationships for the putative PPIs between SOD1 and YWHAE or YWHAZ, we used a breast cancer quantitative proteome database to analyze latent correlations of their protein expression profiles." (PMID 36834640, 2023). "Four proteins (FANCD2, EEF1A1, YWHAE, PGLS) have PPIs with at least one protein in all signatures and one protein in the breast cancer signature (ALDOC) interacts with all other four signatures." (PMID 36329531, 2022). "It has been demonstrated that overexpression of YWHAE strengthens the invasiveness of breast cancer cells 22, but no other studies have probed the impact of YWHAE on the outcome of LUAD." (PMID 38911372, 2024).
schizophrenia (16 papers, 2008 to 2025). A major psychotic disorder characterized by abnormalities in the perception or expression of reality. "This includes the identification of common variants in the YWHAE gene that confer risk of schizophrenia and changes in YWHAE mRNA and 14-3-3ε protein expression levels." (PMID 41218078, 2025). "The YWHAE gene, which encodes the 14–3-3ε protein, is considered a susceptibility gene for schizophrenia." (PMID 38279176, 2024). "The 14-3-3ε isoform is encoded by the YWHAE gene, which has been proposed to be a schizophrenia susceptibility gene." (PMID 35359567, 2022). "This is the first structural MRI study to report the relationship between the functional polymorphism of YWHAE, a gene encoding 14-3-3epsilon, and brain morphology in patients with schizophrenia and healthy controls." (PMID 25105667, 2014). "Finally, in other neural disorders–for instance, suicidal behaviour and schizophrenia, the apoptosis stimulator YWHAE, which encodes eta-polypeptide 14-3-3ε, haplotype (rs1532976), indicated more pronounced suicidal behaviour or risk of disease occurrence." (PMID 35208605, 2022). "Gene-based analyses have shown that common variants in the YWHAE gene contribute to schizophrenia." (PMID 35359567, 2022). "Interestingly, a polymorphism (rs28365859) in YWHAE associated with schizophrenia correlates with differences in volumes of different brain regions in patients." (PMID 32545830, 2020). "YWHAE is a possible susceptibility gene for schizophrenia that encodes 14-3-3epsilon, a Disrupted-in-Schizophrenia 1 (DISC1)-interacting molecule, but the effect of variation in its genotype on brain morphology remains largely unknown." (PMID 25105667, 2014). "Despite these observations supporting the significant role of YWHAE in the neurobiology of schizophrenia, the possible association between variation in its genotype and brain morphology in schizophrenia remains largely unknown." (PMID 25105667, 2014). "Taken together, these data support the contribution of YWHAE to schizophrenia and general brain development." (PMID 32545830, 2020). "YWHAE, a binding partner of DISC1, was also identified as a susceptibility gene for schizophrenia and heterozygous knockout mice of this gene also causes working memory deficits." (PMID 18945333, 2008). "Gene-based analyses using publicly available datasets revealed that common variants in YWHAE contribute to schizophrenia (p = 6.6 × 10−7), whereas ultra-rare variants were found enriched in ASD across the 14-3-3 genes (p = 0.017) and in schizophrenia for YWHAZ (meta-p = 0.017)." (PMID 32545830, 2020). "Several studies have implicated 14-3-3 genes with schizophrenia and bipolar disorder, YWHAE and YWHAZ interact with disrupted in schizophrenia 1 (DISC1), and Ywhae+/– and Ywhaz–/– mice have been shown to display neurodevelopmental and schizophrenia-associated phenotypes." (PMID 27142060, 2016). "These PPIs are of particular interest since genetic association studies have previously implicated YWHAE, YWHAH, and YWHAZ with schizophrenia and bipolar disorder and the PBRM1 locus has surpassed genome-wide significance in both schizophrenia and bipolar disorder GWASs." (PMID 27142060, 2016). "On the basis of the potential role of YWHAE in neuronal development as well as previous MRI findings in schizophrenia, we predicted significant diagnosis-by-genotype interaction predominantly in frontal and temporo–limbic regions, with patients with the protective C allele having a larger GM volume." (PMID 25105667, 2014). "Moreover, an increased expression of SFN and decreased expression of YWHAB, YWHAE, YWHAG and YWHAQ mRNA have been reported in leukocytes of schizophrenia patients." (PMID 32545830, 2020). "However, in line with our results, higher levels of expression of YWHAB, YWHAE, YWHAG and YWHAZ have been described in the brains of schizophrenia patients compared with controls." (PMID 32555255, 2020).
schizophrenia (continued). "Interestingly, five of these genes showed alterations in expression in both ASD and schizophrenia: YWHAB, YWHAE, YWHAH and YWHAZ showed decreased expression whether SFN showed increased expression in both disorders." (PMID 32545830, 2020).
gastric cancer (12 papers, 2013 to 2025). A primary or metastatic malignant neoplasm involving the stomach. "The expression of YWHAE positively correlates with ferroptosis in gastric cancer and is associated with several cancer-related signaling pathways, including MAPK, NF-κB and PI3K." (PMID 39145306, 2024). "Moreover, as YWHAE loss has been reported in gastric cancers and is associated with proteasome-inhibitor resistance in multiple myeloma, CHK1i treatment may be a viable option for patients with these cancers." (PMID 34320214, 2021). "YWHAE silencing induced cell invasion and migration in all gastric cancer cell lines (p<0.05, for all comparisions)." (PMID 27863420, 2016). "Moreover, 4-amino-2-trifluoromethyl-phenyl retinoic acid can induce G0/G1 phase arrest in SGC-7901 gastric cancer cells by downregulating YWHAE." (PMID 34107979, 2021). "In gastric cancer cell lines, YWHAE expression is significantly upregulated, and can inhibit cell proliferation, invasion, and migration by reducing the expression of MYC and CDC25B; whereas MYC induces cell proliferation, invasion, and migration by enhancing CDC25B, and reducing YWHAE expression." (PMID 34107979, 2021). "Additionally, prior research has shown that c-MYC induces the invasion and migration of gastric cancer cells by upregulating CDC25B and downregulating YWHAE expression." (PMID 41184982, 2025). "In addition, YWHAE silencing induces cell proliferation, invasion and migration through the upregulation of CDC25B and MYC in gastric cancer cells." (PMID 35515139, 2022). "YWHAE and PKM2 expression were also induced by IFNα-Le, and knockdown of these proteins has been shown to result in increased invasion, migration and proliferation in gastric cancer cell lines, and inhibition of drug-induced differentiation in leukemic K562 cells." (PMID 31111215, 2019). "For this, we analyzed the YWHAE, CDC25B, and MYC expression in YWHA-silenced, CDC25B-silenced, and MYC-silenced gastric cancer cell lines, as well as in gastric cancer and non-neoplastic gastric samples." (PMID 27863420, 2016). "Furthermore, it has been reported not long ago that YWHAE silencing induced cell proliferation, invasion, and migration through the upregulation of CDC25B and MYC in gastric cancer cells in accordance with our conclusion above." (PMID 35515139, 2022).
colorectal cancer (8 papers, 2013 to 2023). A primary or metastatic malignant neoplasm that affects the colon or rectum. "Functionally and mechanistically, circRNA CBL.11 regulates YWHAE expression by sponging miR-6778-5p directly to suppress cell proliferation in colorectal cancer." (PMID 31438886, 2019).
developmental delay (7 papers, 2012 to 2021). "Isolated duplications of PAFAH1B1 have been associated with mild developmental delay and hypotonia, while isolated duplications of YWHAE have been associated with autism." (PMID 23035971, 2012). "Class II microduplications always involve PAFAH1B1 and may extend to CRK and YWHAE and have been associated to hypotonia, mild developmental, and psychomotor delay." (PMID 23035971, 2012). "The YWHAE gene is closely related to autism, developmental delay, learning delay, and other disorders." (PMID 32951212, 2021). "YWHAE has also been stated as an attractive candidate gene for autism spectrum disorders and developmental delay when duplicated." (PMID 23118768, 2012). "Perhaps our most important finding in this paper is the identification of the YWHAE CNV that appears to be a Chinese-specific polymorphism and not an ASD (or developmental delay)-associated variant." (PMID 25170348, 2014).
endometrial stromal sarcoma (7 papers, 2015 to 2024). "The WHO now recognizes four categories of endometrial stromal tumor, with YWHAE, another 14-3-3 protein translocation, identifying high-grade endometrial stromal sarcoma (HG-ESSs)." (PMID 39061176, 2024). "YWHAE encodes a protein of the 14-3-3 family, and has been found fused to FAM22, or NUTM2A/B/E, in endometrial stromal sarcoma and clear cell sarcoma of the kidney." (PMID 32825119, 2020). "For example, the 14-3-3 protein family member 14-3-3ε (YWHAE) is linked with high-grade and metastatic endometrial stromal sarcomas." (PMID 27223260, 2016). "Furthermore, though both tumors are aggressive, Ewing sarcoma appears to be more aggressive than YWHAE-rearranged high-grade endometrial stromal sarcoma." (PMID 39777304, 2024). "A series of 42 patient tumors diagnosed as endometrial stromal sarcoma (ESS) based on the morphology but negative for JAZF1 and/or YWHAE rearrangement in FISH was analyzed by RNA-sequencing." (PMID 32933053, 2020).
Lissencephaly (7 papers, 2012 to 2022). A spectrum of malformations of cortical development caused by insufficient neuronal migration that subsumes the terms agyria, pachygyria and subcortical band heterotopia. "The lissencephaly phenotype is attributed to deletion of PAFAH1B1, formerly known as LIS1, while disruption of YWHAE, encoding 14–3-3ε, is associated with variable structure brain abnormalities, cognitive impairment and seizures." (PMID 35606653, 2022). "We have previously demonstrated that 14-3-3ε is a critical factor in neuronal migration, indicating that the YWHAE gene is a strong candidate as one of the major genes responsible for the more severe lissencephaly phenotype displayed by MDS patients." (PMID 35053800, 2021). "In particular, deletion of PAFAH1B1 causes isolated lissencephaly while deletions involving both PAFAH1B1 and YWHAE cause Miller-Dieker syndrome." (PMID 23035971, 2012). "It is known that heterozygous 17p13.3 deletions, including PAFAH1B1 (MIM 601545) and YWHAE (MIM 605066) genes, cause two clinically distinct disorders: LSI (isolated lissencephaly) or MDS (Miller-Dieker syndrome), depending on the size of the deletion." (PMID 23035971, 2012). "By contrast, MDS consists of severe classical lissencephaly associated with other symptoms, such as facial anomalies, and MDS patients have larger heterozygous deletions that include the PAFAH1B1 (LIS1) and YWHAE (14-3-3ε) genes, compared with patients with ILS." (PMID 35053800, 2021). "As with lissencephaly, YWHAE, CRK, and PAFAH1B1 have complicated roles in epilepsy." (PMID 29628935, 2018). "Creation of a Crk/Pafah1b1 double knockout could help determine if deletion of these genes contributes to the lissencephaly phenotype in a dose-dependent manner, as this seems to be the case when CRK and YWHAE are deleted together in humans." (PMID 29628935, 2018).
Miller-Dieker syndrome (7 papers, 2012 to 2021). "The overlapping region of loci for exploratory patterns and locomotor activity on chromosome 12 included a mouse homolog of the human YWHAE gene, implicated in the Miller-Dieker syndrome that is located on chromosomal position 17p13.3." (PMID 30559955, 2018). "Miller-Dieker syndrome is a contiguous gene syndrome caused by a microdeletion in 17p13.3, a region that contains LIS1 and YWHAE (which encodes 14-3-3 protein epsilon)." (PMID 26052266, 2015). "The Miller-Dieker syndrome (MDS) is localized in the more distal region 17p13.3 containing the PAFAH1B1 (encoding LIS1) and YWHAE genes." (PMID 23035971, 2012). "This is a rare syndrome wherein the critical region overlaps the deletion region in Miller-Dieker Lissencephaly syndrome (OMIM #247200) involving PAFAH1B1 and/or YWHAE genes on chromosome 17p13.3." (PMID 34465353, 2021). "In humans, YWHAE is absent in sufferers of Miller-Dieker syndrome, which is characterised by severe mental disability." (PMID 27296413, 2016).